COL4A1 (collagen type IV alpha 1 chain)
Diseases named in the same sentence as COL4A1 in open-access papers (continued):
Sharing a sentence is not in itself a finding about the gene and the disease.
myocardial infarction (7 papers, 2016 to 2025). Gross necrosis of the myocardium, as a result of interruption of the blood supply to the area, as in coronary thrombosis. "Col4a1 was associated with several vascular defects, including arterial stiffness and myocardial infarction." (PMID 31331330, 2019). "In analysis limited to 60 CAD genes, we detected strong associations with COL4A2/COL4A1 that also previously showed associations with myocardial infarction and arterial stiffness, as well as coronary artery calcification." (PMID 28642624, 2017). "Associations of COL4A1/COL4A2 reported from meta-analysis of GWAS for coronary artery calcification are of special interest since these genes also showed associations with myocardial infarct in contrast with most other loci associated with coronary artery calcification." (PMID 28642624, 2017). "Following myocardial infarction, miR-543 in exosomes derived from human mesenchymal stem cells targets COL4A1, thereby facilitating the proliferation, migration, invasion, and angiogenesis of heart microvascular endothelial cells." (PMID 40017521, 2025). "Our results demonstrate that the TortA-associated variants in COL4A2 are independent of CAD, myocardial infarction, and blood pressure, and point to a selective role of COL4A2 rather than COL4A1 in the retinal vessels." (PMID 31597446, 2019).
Obesity (7 papers, 2012 to 2024). Accumulation of substantial excess body fat. "Three protein markers: IGFBP1, BPIFB1 and COL4A1 were significantly underexpressed, comparing between participants with obesity and NOH group." (PMID 38548792, 2024). "Note that Col4a1 is found in both groups: as a core gene in the disease-related network and as an obesity-related gene." (PMID 36414820, 2023). "We found that three protein markers that were decreased with obesity group (IGGBP1, COL4A1 and BPFB1) also had consistent associations with cardiometabolic traits, which were in inverse direction compared to other protein markers and clustered in one cluster (turquoise) in hierarchical clustering." (PMID 38548792, 2024). "In summary, we found that obesity at a young age increases collagen IV-IR and lamina densa width and upregulates Col4a1 and Hsp47 expression, suggesting that obesity may be a stimulus for inducing BM production." (PMID 37298161, 2023). "Three proteins underexpressed with obesity (IGFBP1, BPIFB1 and COL4A1) were clustered in the turquoise cluster and overlapped with ER lumen and collagen-containing extracellular matrix GO terms." (PMID 38548792, 2024).
Walker-Warburg syndrome (7 papers, 2011 to 2026). "Some patients with COL4A1 mutations were also diagnosed with Walker–Warburg Syndrome or Muscle–Eye–Brain disease, a distinct form of CMD." (PMID 31623094, 2019). "Type IV collagen (COL4A1) mutations have recently been identified in patients with intracerebral, vascular, renal, ophthalmologic pathologies and congenital muscular dystrophy, consistent with diagnoses of Walker–Warburg Syndrome or Muscle–Eye–Brain disease." (PMID 31623094, 2019).
HANAC syndrome (6 papers, 2016 to 2025). "HANAC syndrome, caused by COL4A1 variants, further highlights the role of collagen IV in maintaining renal architecture and preventing cyst formation." (PMID 40565535, 2025). "In HANAC Syndrome, mutations proved to affect multiple putative integrin binding sites within the COL4A1 protein." (PMID 31623094, 2019). "HANAC syndrome has been proposed as a clinical sub-entity within COL4A1/COL4A2 disease, resulting from mutations located in or close to the integrin-binding CB3 region of the collagen protomer predicted to affect integrin signalling." (PMID 26839400, 2016).
hemorrhage (6 papers, 2011 to 2024). Loss of blood from the vascular compartment to the exterior or into nonvascular body space as a result of rupture or severance of the blood vessels. "In conclusion, we identified a de novo missense variant of the COL4A1 gene in a neonate leading to a COL4A1-related disorder manifesting as multiple intracranial hemorrhages and bilateral congenital cataracts." (PMID 35688819, 2022). "Tissue specific manipulation can provide more focussed analysis of COL4A1 and COL4A2 within brain cell types and the ablation of exon 41 of Col4a1 in astrocytes caused mild intracerebral haemorrhage." (PMID 39707430, 2024).
pancreatic cancer (6 papers, 2013 to 2025). "We found that Ccn1‐deficient pancreatic cancer cells exhibit reduced expression of collagens, including Col4a1, Col4a2, Col5a1, Col6a1, Col6a2, Col6a3, and Col8a1." (PMID 40287974, 2025). "Similarly, mRNA levels of Col5a1, Col6a1, Col6a2, Col6a3, and Col8a1 were significantly reduced in Ccn1‐deficient pancreatic tumors, while Col4a1 and Col4a2 were unaffected." (PMID 40287974, 2025). "Examination of the relationship between gene expression and prognosis using the R2 platform showed that ITGB1 was significantly correlated with the prognosis of pancreatic cancer (p = 0.036), but COL4A1 (p = 0.084), COL4A2 (p = 0.121), and ITGA5 (p = 0.285) were not." (PMID 35648752, 2022). "This identified PEAK1, BMPR2, COL4A1 and ZEB1 as ITGA1 co-expressors in pancreatic cancer and suggested that ITGA1 may play a role in regulating TGFβ responses in pancreatic cancer." (PMID 28855593, 2017).
papillary thyroid cancer (6 papers, 2017 to 2023). "Regulation of COL4A1 expression by miR-21-5p was described previously in papillary thyroid cancer." (PMID 35008952, 2022). "Several studies reported that COL4A1 could be a potential therapeutic target gene in head and neck squamous cell carcinoma, colorectal carcinoma, and thyroid papillary carcinoma." (PMID 32746865, 2020). "It was showed that COL4A1 were overexpressed in papillary thyroid carcinoma." (PMID 29262657, 2017). "A similar phenomenon also exists in hypoxic papillary carcinoma: hypoxic papillary thyroid carcinoma cells secrete exosomes rich in miR-21-5p, thereby promoting endothelial tube formation by inhibiting the expression of TGF-βI and COL4A1." (PMID 35326397, 2022).
bladder cancer (5 papers, 2013 to 2022). "They discovered that COL4A1+COL13A1 was an independent predictor for intravesical recurrence of bladder cancer." (PMID 36035315, 2022). "Novel small-molecule inhibitors, neutralizing antibodies, or anti-sense nucleotides disrupting COL4A1 and COL13A1 should be developed and tested in patients with bladder cancer refractive to conventional therapies." (PMID 28415608, 2017).
congenital cataracts (5 papers, 2014 to 2025). "We report two Palestinian siblings with a pathogenic COL4A1 mutation, presenting with congenital cataracts, seizures, developmental delay, and antenatal intracerebral hemorrhages." (PMID 41001161, 2025). "The presence of cerebrovascular disease and bilateral congenital cataracts, revealed by ophthalmological evaluation, led us to suspect a COL4A1/A2-related disorder." (PMID 35688819, 2022). "COL4A1 mutations cause multi-system disorders in patients, including ASD (congenital cataracts, Axenfeld-Rieger's anomaly, Peter's anomaly and microphthalmia) and congenital or juvenile glaucoma." (PMID 28237965, 2017).
congenital muscular dystrophy (5 papers, 2011 to 2026). A muscular dystrophy that is characterized by diminished muscle tone (hypotonia), progressive muscle weakness and degeneration (atrophy), abnormally fixed joints, spinal rigidity, and delays in reaching motor milestones such as sitting or standing unassisted. "We identify a novel gene implicated in the etiology of MEB/WWS, provide evidence of mechanistic heterogeneity for this subgroup of congenital muscular dystrophies, and develop an assay to test the functional significance of putative COL4A1 mutations." (PMID 21625620, 2011).
dementia (5 papers, 2019 to 2025). Loss of intellectual abilities interfering with an individual's social and occupational functions. "Moreover, Type IV collagen plays a central role in arterial stiffness and dementia pathogenesis, with Col4a1 mutations and dysregulation of its synthesis and degradation closely associated with vascular dysfunction and cognitive decline." (PMID 41302023, 2025).
developmental delay (5 papers, 2018 to 2025). "Despite early seizure control and surgical intervention, he continued to have developmental delays and recurrent seizures, highlighting the progressive nature of COL4A1." (PMID 41001161, 2025). "Here, we describe a two-and-a-half-year-old boy with global developmental delay (GDD) and epileptic encephalopathy secondary to a genetically proven COL4A1 mutation." (PMID 39310498, 2024). "Developmental delay was present in over 80% of individuals with COL4A1/2 with cognitive features; however, no cases of developmental delay were reported for other genes." (PMID 35699195, 2022).
esophageal cancer (5 papers, 2013 to 2025). A primary or metastatic malignant neoplasm involving the esophagus. "A GEO-based prognostic model consisting of six gene products (ARHGAP11A, H1.4, HMGB3, LRIG1, PRR11, and COL4A1) has been shown to be a reliable predictor of esophageal cancer." (PMID 39062899, 2024). "A prognostic model consisting of six gene products (HMGB3, ARHGAP11A, H1.4, LRIG1, PRR11, and COL4A1) is a reliable predictor of esophageal cancer." (PMID 39062899, 2024). "We observed a downregulation of TIMP3 and COL4A1 in normal fibroblasts that were juxtaposed to esophageal cancer cells and this downregulation is consistent with the duration of co-culture and with the increase of miR-21 in the system." (PMID 24039846, 2013). "Decreased levels of COL4A1, DEK, GINS1, HPCAL1, KIF4A and RBMX predicted longer survival in esophageal cancer patients, while overexpression of IGFL1P1, LRRC57A-AS1, SNHG3, ULK3 and ZFYVE19 correlated with longer survival." (PMID 41326355, 2025). "The results showed that COL4A1, DEK, GINS1, HPCAL1, KIF4A and RBMX were significantly increased in esophageal cancer tissues and decreased in the combined treatment group, suggesting that are potential prognostic markers." (PMID 41326355, 2025).
Hypertension (5 papers, 2020 to 2024). The presence of chronic increased pressure in the systemic arterial system. "Risk factors include old age, hypertension and variants in the genes COL4A1/COL4A2 encoding collagen alpha-1(IV) and alpha-2(IV), here termed collagen-IV, which are core components of the basement membrane." (PMID 36205142, 2022). "Col4a1 missense mutations cause early-onset CSVD independent of hypertension, with enhanced vasodilation of small arteries due to endothelial dysfunction, vascular wall thickening and reduced stiffness." (PMID 39216230, 2024). "We analysed four mouse models of SVD (hypertensive BPH mice, Col4a1 mutants, Notch3 mutants and Htra1−/− mice) at different stages for changes in myelin, blood‐brain barrier (BBB) markers, immune cell populations and immune activation." (PMID 39543785, 2024).
intracranial aneurysms (5 papers, 2015 to 2026). "For example, some studies have found that mutations in connective tissue‐related genes, such as COL4A1 and COL4A2, are associated with the pathogenesis of intracranial aneurysms." (PMID 38566524, 2024). "Several of these target genes have been reported to be closely related to the formation, growth and rupture of intracranial aneurysms, including transglutaminase 2 (TGM2), epiregulin (EREG), endothelin-1 (EDN1) and alpha 1 type IV collagen (COL4A1)." (PMID 35242102, 2022).
microphthalmia (5 papers, 2016 to 2024). Congenital or developmental anomaly in which the eyeballs are abnormally small. "This study is the first to map the expression patterns of NID2, LUM, and COL4A1 in stem cell-derived OVs and show their association in microphthalmia." (PMID 38821055, 2024). "The upregulation of LUM and other ECM proteins such as NID2 and COL4A1 in microphthalmia patient OVs in contrast to the loss of Lumican in animal models of increased axial length may be indicative of an inversely proportional relationship between the ECM and axial length." (PMID 38821055, 2024). "In Col4a1+/Δex41 mice between postnatal day (P) 18 and P21, 6 out of 88 eyes had anterior segment dysgenesis, microphthalmia, corneal abrasions or lens opacities that precluded in vivo retinal imaging." (PMID 26813606, 2016). "The overproduction of ECM components, including LUM, NID2, and COL4A1 that encapsulate and infiltrate the OV, may potentially physically limit ocular growth and development, resulting in eye malformations such as microphthalmia." (PMID 38821055, 2024).
ovarian carcinoma (5 papers, 2018 to 2023). A malignant neoplasm originating from the surface ovarian epithelium. "Similarly, COL4A1 and SDC1 expression levels have previously been linked to a dismal prognosis among patients with ovarian cancer." (PMID 37488671, 2023). "It is also noticed that the origins of high COL1A1, COL1A2, and COL3A1 expression positively correlate with fibroblast-specific markers (FAP) and smooth muscle actin (ACTA2), whereas COL4A1, COL4A2, and COL18A1 seem to be predominantly expressed in ovarian cancer cells." (PMID 33026975, 2020).
preeclampsia (5 papers, 2018 to 2023). Preeclampsia is a hypertensive disorder of pregnancy that is characterized by new-onset hypertension with proteinuria presenting after 20 weeks of gestation, and depending on mild or severe forms may initially present with severe headache, visual disturbances, and hyperreflexia. "In this study hESF also had altered production of factors previously identified to be increased in the decidua of women with preeclampsia, including COL4A1, LNPEP, TM9SF2 and COTL1." (PMID 33898438, 2021).
Alport syndrome (4 papers, 2019 to 2025). A rare renal disease characterized by glomerular nephropathy with hematuria progressing to end-stage renal disease (ESRD), frequently associated with sensorineural deafness, and occasionally with ocular anomalies. "Col IV is generated from six kinds of collagen α chains (COL4A1-6) Based on previous studies, COL4A family members have been reported to be involved in the progress of focal segmental glomerulosclerosis, Alport syndrome and cancers." (PMID 40351420, 2025).
cervical carcinoma (4 papers, 2020 to 2024). A carcinoma arising from either the exocervical squamous epithelium or the endocervical glandular epithelium. "The aberrant expression of many of them were positively correlated with the risk of cervical cancer, with the KM curves of four conveying significance, including COL4A1, COL4A2, COL5A1, and COL12A1, which implied their potential application in clinical diagnosis." (PMID 36683048, 2023). "Our data revealed a close positive correlation between the expression of P4HA2 and collagen biosynthesis-related genes (Col4A1, Col5A1 and Col6A1) in cervical cancer, which is also consistent with a previous report of a positive correlation between collagen biosynthesis and P4HA2 in breast cancer." (PMID 32226497, 2020). "The expression levels of Col1A1, Col3A1, Col4A1 and HIF-1α were positively correlated with P4HA2 levels in TCGA cervical cancer cohort (P < 0.001)." (PMID 32226497, 2020).
Cognitive impairment (4 papers, 2020 to 2025). Abnormal cognition is characterized by deficits in thinking, reasoning, or remembering. "Insights from monogenic CSVD syndromes such as CADASIL (NOTCH3 mutations) and COL4A1/2-related angiopathies illuminate pure vascular pathways leading to cognitive impairment." (PMID 41153256, 2025).
diabetic nephropathy (4 papers, 2011 to 2025). "Previous research has demonstrated that the miR-29 family is downregulated in diabetic nephropathy and diabetic cardiomyopathy, where it suppresses collagen gene expression (including COL1A1, COL4A1, and COL6A2) and is closely linked to TGF-β signaling." (PMID 41583295, 2025). "COL4A1 is involved in diabetic nephropathy while COL4A2 is involved in diabetic cardiovascular disease development." (PMID 36118693, 2022). "As evidenced in diabetic nephropathy, the pro-inflammatory cytokine TNF-α suppresses COL4A1 synthesis through the IRE1α/XBP1 endoplasmic reticulum stress pathway." (PMID 40646747, 2025). "Because diabetic nephropathy is characterized by excessive accumulation of ECM in the glomeruli, we also assessed the effect of glucose on mRNA expression of the two main components of ECM in MC: FN1 and COL4A1, and found increases of FN1 expression at 48 h, 72 h, and 96 h, but not at 24 h." (PMID 21526116, 2011).
Intraventricular hemorrhage (4 papers, 2018 to 2025). Bleeding into the ventricles of the brain. "Porencephaly was present in individuals with COL4A1/2 only (61% and 76%, respectively) and intraventricular hemorrhage was present in individuals with COL4A1 only (7%)." (PMID 35699195, 2022).
liver cancer (4 papers, 2009 to 2023). An epithelial or non-epithelial malignant neoplasm that arises from the liver. "Importantly, DHA prevents and reverses fibrosis in a NASH mouse model and decreases expression of two out of three collagen encoding genes (COL1A1, COL1A2, COL4A1) that are upregulated in liver cancer and NASH." (PMID 37859621, 2023). "COL4A1 is dramatically upregulated collagen gene in HCC by screening the expression patterns of all 44 collagen genes in liver cancer from the TCGA-LIHC database." (PMID 32746865, 2020).
metastatic disease (4 papers, 2011 to 2024). "Immunohistochemistry for COL4A1, a low-luminal marker, sustained the association of attenuated luminal phenotype with metastatic disease." (PMID 31936761, 2020).
CARASIL (3 papers, 2019 to 2022). CARASIL is a hereditary cerebral small vessel disease characterized by early-onset gait disturbances, premature scalp alopecia, ischemic stroke, acute mid to lower back pain and progressive cognitive disturbances leading to severe dementia. "A number of different genes come under the umbrella term of vascular leukoencephalopathies, including NOTCH3 (CADASIL), HTRA1 (cerebral autosomal recessive arteriopathy with subcortical infarcts and leukoencephalopathy (CARASIL)), CTSA (CARASAL), COL4A1 and TREX1." (PMID 30467211, 2019).
chronic kidney disease (3 papers, 2015 to 2025). Impairment of the renal function secondary to chronic kidney damage persisting for three or more months. "Moreover, in patients with chronic kidney disease, DNA methylation level of Col4a1 and Col4a2 genes was found to be significantly lower compared to healthy subjects and in correlation with increased mRNA and protein expressions." (PMID 33777319, 2021).
Cirrhosis (3 papers, 2020 to 2025). A chronic disorder of the liver in which liver tissue becomes scarred and is partially replaced by regenerative nodules and fibrotic tissue resulting in loss of liver function. "In the Wurmbach liver (GSE6764), COL4A1 was increased in cirrhosis (fold change =2.997, p = 7.24E-6), liver cell dysplasia (fold change =2.140, p = 7.46E-6), and HCC (fold change =3.711, p = 1.16E-10)." (PMID 31905170, 2020). "The result showed that among the six Col IV isoforms, only COL4A1 and COL4A2 were significantly upregulated from liver preneoplastic lesions (cirrhosis and dysplasia) to HCC." (PMID 31905170, 2020). "In this study, the transcriptional levels of COL4A1 and COL4A2 in approximately 500 clinical samples from two GEO datasets and one TCGA dataset were significantly increased in cirrhosis and HCC." (PMID 31905170, 2020).